CCL19 (C-C motif chemokine ligand 19)
Diseases named in the same sentence as CCL19 in open-access papers (continued):
Sharing a sentence is not in itself a finding about the gene and the disease.
tumor (continued). "Moreover, the transfer of CD45+ EPCs from cachexic HCC mice intravenously to tumour‐free mice caused a decrease in thymocytes compared to mFbs, decreased the mFb/capFb ratio and decreased Mmp9, LtβR and Ccl19 expression in mFbs." (PMID 40665793, 2025). "In contrast, CCR7 and CCL19, which were negatively correlated with the risk score, play roles in immune cell homing and anti-tumor immunity, suggesting that their downregulation in the high-risk group may impair effective immune responses." (PMID 40464853, 2025). "The current consensus is that CCL19 may be a biomarker for metastasis and is associated with tumor promotion, however, the impact of CCR7 signaling in the TME is conflicting because it is expressed on tumor cells and immune cells." (PMID 38786066, 2024). "CCL19 or CCL21 produced by tumor cells is associated with tumor invasion and immune tolerance." (PMID 34689225, 2022). "In addition, we analyzed the association between CCL19 expression and tumor angiogenesis of CRC patients." (PMID 30250188, 2018). "Consequently, this study mainly focuses on the potential molecular mechanisms and signal pathways underlying CCL19-related tumor angiogenesis." (PMID 30250188, 2018). "CCL19/MIP3β expression on tumor cells was associated with higher tumor grade (p = 0.025)." (PMID 21624121, 2011). "Similarly, another group verified that pretreatment the tumor by a recombinant adeno-associated virus carrying the CCL19 gene (AAV-CCL19) could increase the infiltration of GPC3 CAR-T to tumor tissue and significantly prolonged the survival time of mice." (PMID 36093115, 2022). "However, as seen in other cancer types, increased risk of tumor cell migration might also occur with CCL19 administration." (PMID 24762633, 2014). "In tandem, C-C motif chemokine ligand 19 (CCL19), a chemotactic factor, can recruit T cells and dendritic cells (DCs) to migrate and infiltrate tumor sites." (PMID 40177238, 2025). "RNA sequencing data showed a significant upregulation of genes known to increase T and B cell trafficking to tumours (CCL19, CXCL9) and tumour cell killing (GZMB) in these “elite responders”." (PMID 41226343, 2025). "Several studies have observed the immunostimulatory and antitumor functions of CCL19, while other studies have highlighted its role in inhibiting tumor cell apoptosis and promoting metastasis." (PMID 40072746, 2025). "Previous studies have highlighted the role of CCL19 in promoting immune cell migration and infiltration to tumor sites." (PMID 40177238, 2025). "The increased migration and survival of immune cells in the tumor microenvironment (TME), driven by CCL19 and CCL21, are linked to improved therapeutic outcomes, especially when combined with immunotherapies." (PMID 39861713, 2025). "CCL19 can attract dendritic cells and T cells into tumor beds and has been investigated in CAR T cells for solid tumors." (PMID 41181132, 2025). "Mechanistically, the improved efficacy can be attributed, in part, to IL-15 and CCL19 enhancing T-cell infiltration at the tumor site and fortifying resistance to exhaustion within the tumor microenvironment." (PMID 40177238, 2025). "In line with the phenotype data, tumor-primed cDC2s exhibited a lower migratory capacity toward the chemokines CCL19 and CCL21 compared with untreated mature cDC2s." (PMID 40986321, 2025). "CCL19 recruits immune cells, including T cells and dendritic cells, to the tumor microenvironment via CCR7 binding, while promoting their accumulation in lymph nodes and other immune activation sites." (PMID 40895068, 2025). "In this study, we engineered CAR-T cells directed against EGFRvIII to secret human IL-15 and CCL19 and assessed their anti-tumor efficacy against GBM in an orthotopic mouse model." (PMID 40177238, 2025). "A significant positive correlation between activated B cells and CCL19 was observed in this study, highlighting CCL19’s potential role in modulating the tumor immune landscape." (PMID 40895068, 2025).
tumor (continued). "Abundance of LA in the tumor exterior vs tumor interior in our and other studies can drive the migration of immature DCs along outward CCL19/CCL21 gradients, and their accumulation and maturation within LA in peritumoral compartments (OM, PT)." (PMID 41410751, 2025). "Compared with the peritumor area, CCL21, CCL19 and Pecam1 were more highly expressed in the tumor area, whereas Lyve1 had lower expression." (PMID 40685403, 2025). "Compared to the control group, combination treatment significantly increased the expression of Ifng, Tnf, Gzmb, Cxcr3, Cxcl11 and Ccl19 in the tumor, suggesting a more inflammatory TME." (PMID 39816690, 2025). "CCR7 has long been established to be necessary for migration of cDC1s to LNs but has more recently also been suggested to be expressed in activated cDC1s that are retained in the tumours, potentially by CCL19‐expressing fibroblasts." (PMID 40745918, 2025). "Results from coculture and cell transfer assays suggest that cancer cachexic CD45+ erythroid progenitor cells (EPCs) induce the death of CD34+ progenitor cells and decrease the number of LtβR+, Mmp9+ and Ccl19+ mFbs in tumour‐free mice." (PMID 40665793, 2025). "The IGLoS signature also demonstrated significant differences between tumor and normal tissues in pan‐cancer, among which the expression of CCL19 was lower in most tumors, while the other five genes showed higher expression in most tumors." (PMID 40714831, 2025). "In the meanwhile, DKK1+ tumor cells accumulated in the tumor area in immune-exclusion samples, especially in the tumor boundary, inhibiting the infiltration of CCL19+ fibroblasts and plasma cells into tumor area." (PMID 39505867, 2024). "This accumulation impeded the infiltration of CCL19+ fibroblasts and plasma cells into the tumor area." (PMID 39505867, 2024). "Our analysis unveiled the co-localization of CCL19+ fibroblasts and plasma cells within the tumor area of samples exhibiting high intra-tumor immune infiltration." (PMID 39505867, 2024). "Our observations revealed IGHG1+ plasma cells scattered within the tumor area, with CCL19 exhibiting high expression levels around these plasma cells, suggesting its role as a supportive component for plasma cells." (PMID 39505867, 2024). "Subsequently, we observed the accumulation of CCL19+ fibroblasts within the plasma cell+ intra-tumor immune infiltration." (PMID 39505867, 2024). "In immune exclusion samples, DKK1 was highly expressed in the tumor area, where plasma cells and CCL19+ fibroblasts were excluded and situated along the tumor boundary." (PMID 39505867, 2024). "The TLS score exhibited a similar spatial distribution as plasma cells and CCL19+ fibroblasts, showing low expression levels in immune exclusion tumor areas." (PMID 39505867, 2024). "CCL19 can induce anti-tumor immune responses and inhibit angiogenesis, exerting tumor suppressor functions, and also induce inflammation, cell growth, and metastasis." (PMID 39682471, 2024). "CCL19 and CCL21 also influence lymphocyte migration through high endothelial venules (HEVs), which are critical in tumor immunosurveillance and are linked to the overexpression of lymphoid chemokines and genes related to Th1 and naïve T cells." (PMID 39766071, 2024). "In order to optimize therapeutic effectiveness, CAR-T cells expressing cytokines like IL-7 and chemokines like CCL19 have been engineered, significantly enhancing their anti-tumor capabilities." (PMID 38791916, 2024). "Slit2 treatment further induced gene expression associated with a tumor-promoting macrophage phenotype by activating MMP-9, VEGF-a, Mrc1, Ccl19, TGF-β1, IL-10, Cd209a, and Arg1." (PMID 39456164, 2024). "Intratumoral injection of CAR-GPC3 T cells secreting IL-7 and CCL19 resulted in complete tumor regression of an advanced HCC patient." (PMID 38679698, 2024).
tumor (continued). "On the other hand, following three treatments with HER2 scFv-CCL19-IL-7, there was a marked reduction in tumour volume and consistent inhibition of tumour growth, indicating potent and sustained tumour suppression." (PMID 38675377, 2024). "When administered without prior lymphodepletion, CAR T cells were potentially modified to generate chemokine ligands like CCL19 to promote the recruitment of endogenous T cells and dendritic cells to tumor locations." (PMID 38693513, 2024). "CAR-T cells secreting CCL19 and IL-7 have been proven to have higher infiltration of DCs and T cells in tumor tissue." (PMID 38475811, 2024). "Comprehensive experimental validations are necessary to interpret the role of DKK1+ tumor cells in impeding the infiltration of CCL19+ fibroblasts and plasma cells into the tumor area within the context of the immune response." (PMID 39505867, 2024). "CCL19 emerges as a promoter of tumor cell growth, invasion, and metastasis, alongside its remarkable ability to stimulate immune cells within the tumor microenvironment." (PMID 37944262, 2023). "We constructed the first prognostic model based on the CCR7/CCL19 chemokine axis in BC and explored its role in immune infiltration, tumor microenvironment, and HLA genes." (PMID 37864213, 2023). "CCL19, CXCL10, and CXCL13 transcript expression levels were significantly associated with tumor stage (lowest levels in stage 2) in the TCGA-SKCM cohort." (PMID 37435077, 2023). "And in a patient with advanced PC, anti-MSLN-IL-7/CCL19 CAR-T cellular therapy resulted in almost complete tumor disappearance 240 days post-intravenous infusion." (PMID 37081982, 2023). "Studies have shown that EV-packaged CCR7-induced tumor cells recognizes and accumulates toward lymphogenic CCL19 and CCL21, thereby promoting preferential tumor cell localization in sentinel LNs1." (PMID 36971125, 2023). "Recent research has delved into the intricate relationship between CCL19 expression and tumor prognosis, shedding light on its potential significance across various cancer types." (PMID 37944262, 2023). "Co-administration of pCCL19 and NT_Neo5 and treatment with CCL19_Neo5 led to complete tumor prevention in most animals, hampering the analysis of the potential impact of the link between CCL19 and the neoepitopes in preventing tumor development." (PMID 37720215, 2023). "Our initial histological observations revealed intriguing disparities in CCL19 expression between normal and tumor tissues." (PMID 37944262, 2023). "Other studies have found that in a patient with late-stage HCC, anti-GPC3 IL-7/CCL19 CAR-T therapy resulted in complete tumor disappearance 30 days post-intra-tumor injection." (PMID 37081982, 2023). "CCL19 can enhance tumor T cell and dendritic cell-infiltration levels and PD-1/PD-L1 inhibitors' therapeutic effects." (PMID 37841886, 2023). "The results showed that the percentage of CCL19 + cells were positively correlated with the percentage of FOXP3 + cells in tumor tissues." (PMID 37208608, 2023). "All APC-targeting pDNA vaccines conferred superior tumor control compared to the mock control with CCL19, CCL20, and CCL21_Neo5 displaying statistically significant improvements." (PMID 37720215, 2023). "Extensive research has unveiled a multifaceted role for CCL19 within this context, with far-reaching implications for tumor progression." (PMID 37944262, 2023). "In conclusion, we constructed the first prognostic model based on the CCR7/CCL19 chemokine axis in BC and explored its role in immune infiltration, tumor microenvironment, and HLA genes." (PMID 37864213, 2023). "In colorectal cancer, mregDCs expressed LGALS9 and PD‐L1 (CD274) in tumour tissues from patients who received presurgical chemotherapy or not, while the production of chemokines recruiting Tregs, such as CCL19 and CCL10, was reduced in the treated patients." (PMID 36808888, 2023).
tumor (continued). "Treatment with anti‐GM2 IL‐7/CCL19‐producing CAR‐T cells induced complete tumor regression along with an abundant T cell infiltration into the solid tumor tissue and long‐term memory responses, without any detectable adverse events." (PMID 37031457, 2023). "conclude that the co-delivery of two different DNA plasmids encoding CCL19 and the immunogenic cancer antigen HER2 boosts immunogenicity and tumor protection." (PMID 37720215, 2023). "In the context of tumors, CCL19 often emerges as a key player, emanating not only from tumor cells but also from other constituents of the tumor microenvironment." (PMID 37944262, 2023). "Our groundbreaking research marks the first of its kind, revealing CCL19 as a promising tumor suppressor gene with profound prognostic value in BRCA and OV." (PMID 37944262, 2023). "In this segment, we sought to evaluate the relationship between CCL19 expression, the tumor immune microenvironment, and patient prognosis." (PMID 37944262, 2023). "A low expression of CCL19 in CRC is related to tumor angiogenesis, and a high expression of CCL19 inhibits CRC angiogenesis by promoting miR-206, thus inhibiting the Met/ERK/Elk-1/HIF-1α/VEGF-A pathway." (PMID 35935996, 2022). "Tumoral overexpression of CCL19, CCL21, and XCL1 significantly increased ratios of total cDCs, cDC1, and cDC2 subtypes among CD45+ leukocytes in the TME, as compared to the empty vector control tumors." (PMID 36654820, 2022). "Introduction of exogenous genes into tumor cells by recombinant plasmid techniques (e.g., lentiviral transfection) is another way to achieve elevated concentrations of CCL19/CCL21 protein." (PMID 35702353, 2022). "According to this report, the intratumor administration of GPC3-redirected CCL19-IL-7 CAR-Ts into a patient with advanced HCC resulted in complete tumor rejection within 30 days following the therapy." (PMID 35634281, 2022). "CCL19 can make chemotactic DC cells and αβT cells infiltrate into tumor tissue, and those αβT cells can be activated by the APC cells such as DC cells and γδT cells and played a synergistic role in fighting against the FRa-negative TNBC cells." (PMID 35295709, 2022). "In vivo experiments have shown that CAR-T expressing CCL19 can consistently and conditionally exert beneficial tumor-suppressive effects." (PMID 35990619, 2022). "As in the previous study, IL-7/CCL19-producing human CAR-T cells exerted a significant inhibition of tumor growth and prolonged survival of treated mice." (PMID 35211124, 2022). "CAR T cells engineered to constitutively secret IL-7 and CCL19, recreating the T cell zone in lymphoid organs within the tumor, improved anti-tumor immunity in murine solid tumor models." (PMID 36366354, 2022). "Subsequent studies have also confirmed that CCL19 can be used as an adjuvant for immunization with intradermal gene guns in a Her2/neu mouse tumor model, with enhanced vaccine efficacy." (PMID 35770088, 2022). "The results showed that CAFs in P-LNs were associated with the high expression of NFIB, IGLC2, IGHG4, C7, and CCL19, while CAFs in tumor 3 had high expression of DIO2, LGALS1, WNT5A, NEAT1, and MMP11 in the tumor." (PMID 36569924, 2022). "On the other hand, the CCL19/CCR7 axis is involved in the modulation of the immune response in a growing tumor." (PMID 35160116, 2022). "Taking the results from CT26 and MC38 models together, CCL19 seemed to be the most potent anti-tumor chemokine among the four." (PMID 36654820, 2022). "Altogether, these results suggest that NFAT signaling-regulated CCL19 can be induced by tumor cell-surface mesothelin in vitro." (PMID 35990619, 2022). "VEGFC accumulated in the tumor context induces tumor lymphatic vessels to release chemokines such as CCL19 and CCL21 that can attract tumor cells through their binding to CCR7." (PMID 36612017, 2022). "The first of these is to increase CCL19/21 concentration within the TME to sharpen the immune response to tumor." (PMID 35702353, 2022).
tumor (continued). "Then, we evaluated the efficacy of HSV-2 vectors expressing IL-12, IL-15, PD-1v, GM-CSF, and IL7 × CCL19 using syngeneic CT26 tumor-bearing model." (PMID 35459242, 2022). "In this study, CCL19 was introduced to the NKG2D CAR construct to generate 15×19 CAR T cells, which secreted high levels of CCL19 following recognition of tumor antigens." (PMID 36618357, 2022). "Expression of CCL19 (which expressed a 2.6-fold-change in MCTVT) and C5AR1 (which expressed a 2.28-fold-change in MCTVT) is highly associated with the advanced tumour stage and promotes cell proliferation in several cancers, leading to poor patient outcomes." (PMID 34980125, 2022). "In both CT26 and MC38 tumor models of our study, CCL19 and CCL21 showed powerful anti-tumor activities, with CCL19 being more potent than CCL21, although the overexpression levels varied in the two tumor cell lines." (PMID 36654820, 2022). "CAR-T cells were then co-cultured with these tumor cells for 16 h, before the concentration of CCL19 secreted into the supernatant was detected." (PMID 35990619, 2022). "Induced expression of CCL19 can promote the anti-tumor ability of CAR-T cells by increasing their infiltrative ability." (PMID 35990619, 2022). "The combination therapy of oHSV2-IL12, -IL15, GM-CSF, -PD1v, and IL7 × CCL19 exhibited the highest tumor inhibition efficacy compared with the treatment of single OV or two OVs combination." (PMID 35459242, 2022). "The rationale is that only CAR-T cells that have successfully infiltrated into the tumor tissues can be activated by the tumor cells and release CCL19 to recruit other immune cells for infiltration." (PMID 35990619, 2022). "CCL19 was reported previously to recruit Dendritic cells (DCs) and T cells in paracancerous tissues to tumor tissues." (PMID 36189258, 2022). "In the present study, inducing the expression of CCL19 effectively directed the chemotactic CAR-T cells to specifically infiltrate the PC tumor tissue." (PMID 35990619, 2022). "A significant negative correlation was found between the expression level of CCR7 and CCL19 and miR let-7a in tumor tissue (p = 0.0007, rho = −0.426 and p = 0.00002, rho = −0.521, respectively, Spearman’s rank correlation)." (PMID 35160116, 2022). "This research is a continuation and extension of our earlier study, the aim of which was to evaluate changes in the expression level of CCR7 and CCL19 in tumor tissue and of two regulatory miRNAs of these genes (miR let-7a and miR-335) in serum exosomes." (PMID 35160116, 2022). "In summary, the NFAT-regulated expression of CCL19 in mesothelin-targeting CAR-T cells in the present study was able to effectively lyse the PC tumor cells." (PMID 35990619, 2022). "IL7 co-expressed with C-C motif chemokine ligand-19 (CCL19) or CCL21 produced an improved T cell memory response along with increased chemotaxis to the tumor lesion and enhanced amplification." (PMID 36700225, 2022). "The results suggested that the AAV-mediated expression of CCL19 in tumor cells promoted the infiltration of CAR-T cells into tumor tissues and improved the antitumor activity of CAR-T cell therapy." (PMID 34527749, 2021). "In fact, new generation of CAR-T cell has been engineered to expressed IL-7 and CCL19 to elevate anti-tumor efficacy." (PMID 34544443, 2021). "By analyzing the TCGA and GEO database and applying ESTIMATE algorithm and a series of bioinformatic methods, we obtained tumor microenvironment associated genes (CD79A, CXCL13, IL6 and CCL19), which were related to the clinical outcome of PRCC patients." (PMID 33993869, 2021). "The exception was CCL19, expressed at a similar level in tumor and normal tissue, and significantly downregulated in tumors compared to normal mucosa." (PMID 34885960, 2021). "More recently, CAR T cells secreting CCL19 are being evaluated to potentially increase tumor infiltration rate of dendritic cells and T cells, and improve anti-tumor immunity." (PMID 33428680, 2021).